NEK8 (NIMA related kinase 8)
Diseases named in the same sentence as NEK8 in open-access papers (continued):
Sharing a sentence is not in itself a finding about the gene and the disease.
cystic kidney disease (6 papers, 2012 to 2025). A congenital or acquired kidney disorder characterized by the presence of renal cysts. "Two of these genes have previously shown to be associated with cystic kidney disease in mammals, namely, the genes coding for the Nek8 protein and for the intraflagellar transport protein 20 (IFT20)." (PMID 22899815, 2012). "This study found a novel SNP mutation (R650C) located within the Nek8 gene on rat Chr 10 is responsible for the autosomal recessive cystic kidney disease phenotype identified in the LPK rat." (PMID 22899815, 2012). "Thus, loss of function of Nek8 has linked replication stress to functions of the primary cilia and genome stability as a path to developing ciliopathies, such as cystic kidney disease." (PMID 34828368, 2021). "Mice of the 4 genotypes — WT, Nek8+/jckeIF2α+/SA (double heterozygotes), Nek8jck/jckeIF2α+/+ (jck), and jckeIF2α+/SA — were generated, and renal cyst burden was determined by ultrasonography at 3 months of age." (PMID 36326820, 2022). "Proteomics of renal cysts in jck mice revealed upregulation of vimentin, sorcin, and galectin-1, hinting at a possible role of Nek8 as a check point regulator of mitotic spindle, through interactions with the polycystin complex." (PMID 34828368, 2021). "CDK inhibitors, particularly roscovitine, have demonstrated efficacy in targeting dysregulated cell cycle progression, effectively arresting kidney volume expansion and cyst progression in jck/Nek8/Nphp9 mouse models and attenuating renal cyst progression in Cep164-knockout mice." (PMID 40806500, 2025). "Analyses indicated 13 genes, in addition to Nek8 and Ift20 within this area that could potentially result in cystic kidney disease, namely: RGD1309077Phf12, Flot2, Spag5, Sdf2, Supt6h, Proca1, Traf4, Sarm1, Nlk and Ksr1." (PMID 22899815, 2012). "A class of bioactive lipid metabolites called cyclooxygenase (COX) oxylipins (e.g., prostaglandins, leukotrienes) has been shown to be elevated in diseased kidneys of rodent models of NPH (pcy/Nphp3 and jck/Nek8/Nphp9 mice and Han:SPRD-Cy/Anks6/Nphp16 rats) and other cystic kidney diseases." (PMID 34055783, 2021).
cyst (4 papers, 2012 to 2025). A sac-like closed membranous structure that may be empty or contain fluid or amorphous material. "In contrast, inhibition of Hh signaling using GLI and SMO small molecule antagonists Gant61 and Sant2 respectively prevented cyst formation in kidney explants from Ttc21b/Ift139-conditional knockout, jck/Nek8/Nphp9 and Pkd1 mutant mice." (PMID 34055783, 2021). "Another study in jck/Nek8/Nphp9 mice demonstrated that roscovitine ameliorated the elongated cilia phenotype and restored tubular epithelial differentiation, while conditional inactivation of CDK5 reduced cilia length, total kidney volume and cyst formation." (PMID 34055783, 2021). "Furthermore, a study using LPK/Nek8/Nphp9 mutant rats found that treatment with the immunomodulatory drug dimethyl fumarate, which activates the Nrf2 pathway and inhibits NF-kB signaling, reduced macrophage infiltration but did not ameliorate cyst progression or renal insufficiency." (PMID 34055783, 2021).
cystic kidneys (4 papers, 2016 to 2025). "Mouse models of InvsC defects (Invs, pcy/Nphp3, jck/Nek8/Nphp9 and Anks6/Nphp16-mutated mice) show enlarged cystic kidneys characteristic of infantile NPH, although pcy/Nphp3 and Anks6/Nphp16 mice have slow disease progression and (late stage) tubulointerstitial fibrosis." (PMID 34055783, 2021). "This is in agreement with the phenotype of Anks6Streaker mice whose Anks6 mutation (p.M187K) decreases the binding to and activation of Nek8 and leads to cystic kidneys, situs inversus and congenital heart defects, thus mimicking the phenotype of patients with NEK8 mutations." (PMID 26967905, 2016). "Interestingly, we also identified a homozygous frameshift mutation (c.1010_1011del, p.G337Afs*16, family 6) in ANKS6 in a fetus whose phenotype was similar to that of NEK8 loss of function cases, i.e. enlarged cystic kidneys associated with enlarged fibrotic pancreas, situs inversus and cardiopathy." (PMID 26967905, 2016). "YAP imbalance was also observed in enlarged spheroids of Nek8-invalidated renal epithelial cells grown in 3D culture, as well as in cystic kidneys of Jck mice." (PMID 26967905, 2016). "Similarly, jck/Nek8/Nphp9 mice, which show enlarged cystic kidneys and rapid disease progression, have been used as a model for (AR)PKD." (PMID 34055783, 2021). "Interestingly, NEK8/NPHP9 was shown to positively regulate polycystin-2 expression and ciliary localization, in agreement with the cystic kidneys observed in infantile NPH linked to mutations in InvsC genes." (PMID 34055783, 2021).
renal cystic dysplasia (3 papers, 2016 to 2022). "NEK8/NPHP9 mutations were identified in five cases with severe overlapping phenotypes including renal cystic dysplasia/hypodysplasia, situs inversus, cardiopathy with hypertrophic septum and bile duct paucity." (PMID 26967905, 2016). "Indeed, involvement of Nek8 in the Hippo pathway was further expanded when it was shown that Nek8 mutations contribute to renal cystic dysplasia via deregulation of YAP." (PMID 35409400, 2022).
type 2 diabetes (3 papers, 2021 to 2023). "Moreover, NEK8 overexpression has been linked to obesity associated with type 2 diabetes (T2DM) by stimulating adipocyte proliferation." (PMID 37596667, 2023). "In the present study, we first investigated the functional role of NEK8 in adipocyte function and its association with TAZ using an in vivo model of HFD-induced type 2 diabetes in C57/BL6 mice." (PMID 36506932, 2022). "This research would be helpful for understanding the mechanisms of NEK8 in type 2 diabetes- (T2DM-) related obesity." (PMID 36506932, 2022).
breast tumors (2 papers, 2014 to 2023). "Elevated expression of NEK8 has been observed in primary breast tumours and NEK8 is associated with genetic instability and mutations." (PMID 37100815, 2023). "Similarly, our ongoing research shows that NEK8 expression is upregulated in primary breast tumours compared with that in normal breast tissues (manuscript under preparation)." (PMID 37100815, 2023).
colorectal cancer (2 papers, 2020 to 2023). A primary or metastatic malignant neoplasm that affects the colon or rectum. "Then, in vivo and in vitro experiments demonstrated that NEK8 expression was positively correlated with colorectal cancer proliferation, and loss of NKE8 inhibited the growth of the subcutaneous transplanted tumors in the nude mice." (PMID 37596667, 2023). "We substantiated that loss of NEK8 could significantly inhibit the proliferation ability of colorectal cancer cells in vitro by CCK8 assays." (PMID 37596667, 2023). "Overall, these findings provided the theoretical basis for pharmacologically inhibiting the enzymatic activity of NEK8 for colorectal cancer treatment." (PMID 37596667, 2023). "To assess the role of NEK8 in colorectal cancer progression, we first analyzed the expression level of NEK8 in colorectal cancer and normal colorectal tissues using the GEPIA and TCGA databases." (PMID 37596667, 2023). "Results showed that NEK8 was upregulated in colorectal cancer tissues compared with adjacent normal tissues." (PMID 37596667, 2023). "Herein, we substantiated that NEK8 was upregulated in colorectal cancer compared with normal colorectal tissues." (PMID 37596667, 2023). "Taken together, our findings revealed that NEK8 is upregulated in colorectal cancer and suggest its potential role as an oncogenic factor in driving the progression of colorectal cancer." (PMID 37596667, 2023). "Next, we co-cultured EdU and SW48 or Lovo cell lines to validate the function of NEK8 in colorectal cancer cells." (PMID 37596667, 2023). "Next, we detected the expression level of NEK8 in 14 pairs of colorectal cancer and adjacent normal tissues using western blots." (PMID 37596667, 2023). "Next, we conducted animal experiments to assess the biological function of NEK8 in colorectal cancer in vivo." (PMID 37596667, 2023). "In our research, we innovatively revealed that NEK8 was significantly upregulated in colorectal cancer and positively regulated colorectal cancer cell proliferation." (PMID 37596667, 2023). "To clarify the role of NEK8 in colorectal cancer, we first constructed SW48 or Lovo cell lines stably expressing Vector or NEK8." (PMID 37596667, 2023). "We found a higher expression level of NEK8 in colorectal cancer compared with normal colorectal tissues." (PMID 37596667, 2023). "To further validate the pro-proliferation ability of NEK8 in colorectal cancer cells, we knocked out NEK8 expression using the Crispr-cas9 system in SW48 or Lovo cancer cells." (PMID 37596667, 2023). "We also demonstrated that NEK8-induced colorectal cancer proliferation relied on the serine 405 phosphorylation of c-MYC." (PMID 37596667, 2023). "Further, IHC assays were conducted to investigate the expression level of NEK8 in 69 pairs of colorectal cancer and adjacent normal tissues." (PMID 37596667, 2023). "Consistently, we investigated the correlation between overall survival and NEK8 expression in 69 cases of colorectal cancer patients." (PMID 37596667, 2023). "We corroborated that NEK8-mediated colorectal cancer cell proliferation depends on the phosphorylation of c-MYC at the serine 405 sites." (PMID 37596667, 2023). "Taken together, these data revealed that NEK8 could positively regulate the proliferation ability of colorectal cancer cells in vivo or in vitro." (PMID 37596667, 2023). "Besides, we uncovered that NEK8-induced cancer cell proliferation and colorectal cancer progression depend on the serine 405 phosphorylation of MYC by in vivo or in vitro assays." (PMID 37596667, 2023). "Overall, these results showed that NEK8 overexpression could significantly enhance the proliferation ability of colorectal cancer cells." (PMID 37596667, 2023). "Based on these findings, we propose that the NEK8/c-MYC signaling pathway could be a potential therapeutic target for colorectal cancer." (PMID 37596667, 2023).
colorectal cancer (continued). "Collectively, these findings imply that the NEK8/MYC signaling pathway might be a novel target for colorectal cancer treatment." (PMID 37596667, 2023). "In conclusion, we innovatively revealed the biological function of NEK8 in colorectal cancer." (PMID 37596667, 2023). "Therefore, it is important to investigate whether NEK8 plays a role in the development and progression of colorectal cancer." (PMID 37596667, 2023). "Our findings shed light on the role of NEK8/MYC signaling in CRC progression, offering a novel and helpful target for colorectal cancer treatment." (PMID 37596667, 2023). "To further confirm the correlation between NEK8 and c-MYC, we analyzed the expression level of NEK8 and c-MYC in 69 cases of colorectal cancer tissues." (PMID 37596667, 2023). "To further clarify the correlation between NEK8 signaling and MYC signaling in colorectal cancer progress, we constructed SW48 and Lovo cells stably expressing Vector + shNC, NEK8 + shNC, NEK8 + shc-MYC#1, NEK8 + shc-MYC#2." (PMID 37596667, 2023). "Moreover, RT-PCR demonstrated that colorectal cancer tissues had higher mRNA expression of NEK8 than adjacent normal tissues." (PMID 37596667, 2023). "However, no research has assessed the biological role of NEK8 in colorectal cancer." (PMID 37596667, 2023).
glioblastoma (2 papers, 2021 to 2023). The most malignant astrocytic tumor (WHO grade IV). "The expression level of NEK8 was significantly higher in glioblastoma than in other histological types (p < 0.001; Kruskal‐Wallis rank‐sum test)." (PMID 34374193, 2021). "In the high expression group, glioblastoma was most frequent, and a similar distribution of astrocytoma and oligodendroglioma was discovered both in the low and high NEK8 expression group (p < 0.001)." (PMID 34374193, 2021). "As determined by the Wilcoxon rank‐sum test, NEK8 expression was upregulated in the majority of cancer types, including glioblastoma and low‐grade glioma, compared with normal tissues." (PMID 34374193, 2021). "Besides, we found that higher NEK8 expression had poorer overall survival time in other kinds of tumors, such as glioblastoma, low-grade glioma, and uveal melanoma." (PMID 37596667, 2023).
glioma (2 papers, 2021 to 2023). A benign or malignant brain and spinal cord tumor that arises from glial cells (astrocytes, oligodendrocytes, ependymal cells). "We elucidated that NEK8 expression is increased in glioma and is associated with the WHO grade and prognosis." (PMID 34374193, 2021). "We found that elevated NEK8 expression in glioma is associated with various clinical and pathological parameters (WHO grade, histological type, IDH, EGFR, PIK3CA status and primary therapy outcome) and survival time." (PMID 34374193, 2021). "Our results provide potential therapeutic targets in glioma, as well as novel insights into the molecular mechanisms underlying the effects of NEK8." (PMID 34374193, 2021). "We further showed that NEK8 expression is elevated in glioma and is associated with the WHO grade." (PMID 34374193, 2021). "Functional enrichment analyses of genes with correlated expression indicated that elevated NEK8 expression is associated with increased immune cell infiltration in glioma and may affect the tumour microenvironment via the regulation of DNA damage/repair." (PMID 34374193, 2021). "Asian expressed high level of NEK8 more easily in glioma, while a nearly equal distribution of NEK8 was found in White (p = 0.017)." (PMID 34374193, 2021). "The expression level of NEK8 was significantly higher in Asian and black or African American patients with glioma than that observed with white (p = 0.037)." (PMID 34374193, 2021). "Collectively, these results showed that NEK8 is a potential prognostic marker for patients with glioma." (PMID 34374193, 2021). "Although our results improve our understanding of the relationship between NEK8 and the pathogenesis of glioma, the study had some limitations." (PMID 34374193, 2021). "We then performed a Kaplan‐Meier survival analysis using data obtained from TCGA to investigate the prognostic value of NEK8 in glioma." (PMID 34374193, 2021). "In this study, we investigated NEK8 expression and its prognostic value in glioma using clinical samples and data from The Cancer Genome Atlas (TCGA) and Chinese Glioma Genome Atlas (CGGA)." (PMID 34374193, 2021). "There were significant differences in expression of NK cells and Th2 cells in the high and low NEK8 expression gliomas." (PMID 34374193, 2021). "IHC staining suggested that patients with high level of positive NEK8 expression corresponded to the high glioma grade and further confirmed by the ImageJ software semi‐quantitative expression analysis." (PMID 34374193, 2021). "Using a bioinformatics approach and RNA‐seq data from public databases, we found that NEK8 expression is elevated in glioma tissues; we further verified this result by RT‐PCR, Western blotting and immunochemistry using clinical samples." (PMID 34374193, 2021). "In the current study, we evaluated the prognostic value of NEK8, as well as its role in the pathogenesis of glioma." (PMID 34374193, 2021). "With respect to biological functions, we elucidated that NEK8 influences immune cell infiltration into the glioma microenvironment via the regulation of DDR." (PMID 34374193, 2021). "Therefore, it is necessary to explore the mechanism by which NEK8 influences the infiltration of immune cells in the glioma microenvironment, in future research." (PMID 34374193, 2021). "Broadly, further analyses of the precise role of NEK8 in glioma are needed." (PMID 34374193, 2021). "The effects of NEK8 in glioma may be mediated by alterations in immune cell infiltration into the tumour microenvironment via the regulation of DDR." (PMID 34374193, 2021). "Additionally, a KEGG functional analysis suggested that NEK8 is involved in the microenvironment of glioma." (PMID 34374193, 2021). "We also detected that NEK8 affects the infiltration of immune cells in the glioma microenvironment." (PMID 34374193, 2021). "Our bioinformatics analyses revealed that NEK8 is closely correlated with DDR in glioma." (PMID 34374193, 2021).
glioma (continued). "Based on these analyses, NEK8 may influence the glioma microenvironment via the DNA damage response (DDR) pathway." (PMID 34374193, 2021). "Finally, a Kaplan‐Meier prognostic analysis suggested that high NEK8 expression is associated with a worse PFI and DSS in the different subgroups of glioma (p < 0.05)." (PMID 34374193, 2021). "Additionally, there is evidence suggesting that NEK8 might influence the infiltration of immune cells in glioma." (PMID 37596667, 2023). "In addition, we elucidated that NEK8 might modulate the glioma microenvironment via the DDR pathway and, therefore, is a target for suppressing DDR in glioma." (PMID 34374193, 2021). "NEK8 might promote the development of glioma via DNA damage/repair." (PMID 34374193, 2021). "However, the fundamental mechanism by which NEK8 contributes to glioma is still poorly understood." (PMID 34374193, 2021). "A Western blotting assay showed that NEK8 protein expression was significantly upregulated in grade III and IV glioma samples compared with non‐tumour." (PMID 34374193, 2021). "NEK8 is involved in multiple biological processes in a variety of cancers; however, its role in glioma is still not clear." (PMID 34374193, 2021). "However, the expression of NEK8 and its clinical prognostic value on glioma has not been investigated." (PMID 34374193, 2021).
invasive breast carcinoma (2 papers, 2023 to 2025). A carcinoma that infiltrates the breast parenchyma. "However, studying overexpression of NEK8 may provide important clinical relevance due to the prevalence of NEK8 overexpression in invasive breast cancer." (PMID 39975112, 2025). "NEK8 overexpression has been found in a high percentage of non-specific invasive breast cancer." (PMID 39975112, 2025).
Kidney Cyst (2 papers, 2023). Abnormal fluid filled sac within the kidney, either acquired or congenital. "While DNAJB11 is a known disease-causing gene of ADPKD, and kidney cysts can develop in patients who are heterozygous for a pathogenic variant in PKHD1, more evidence is required to determine whether heterozygous NEK8 and WDR19 pathogenic variants can mimic the ADPKD phenotype." (PMID 36833371, 2023). "In mouse, Anks6, Invs, Nphp3, and Nek8 mutants develop kidney cysts, while mutants of several other NPHP genes show no obvious kidney phenotypes." (PMID 36920028, 2023).
lymph node metastasis (2 papers, 2025). "Additionally, higher NEK8 expression was significantly associated with lymph node metastasis." (PMID 39762761, 2025).
renal carcinoma (2 papers, 2020). A carcinoma arising from the epithelium of the renal parenchyma or the renal pelvis. "pVHL is thought to either downregulate NEK8 through HIF-1α to maintain the primary cilia structure in human renal cancer cells or to directly ubiquitinate NEK8 for proteosomal degradation." (PMID 32603638, 2020). "Renal cancer cells with VHL defects presented a high expression of NEK8, suggesting that VHL may downregulate NEK8 in these cells." (PMID 32294979, 2020).
adenoma (1 paper, 2023). A neoplasm arising from the epithelium. "We collected the resected carcinoma tissues from CRC patients and conducted immunohistochemical (IHC) staining analysis to examine the expression of some representative genes including NEK8, CHRM3, ANO7, B3GNT6, NEURL1, ODC1 and KCNMA1 in colon normal tissue, adenoma tissue and carcinoma tissues." (PMID 36944972, 2023).
astrocytoma (1 paper, 2021). "We also discovered that higher NEK8 expression related to a poorer OS both in astrocytoma and oligodendroglioma." (PMID 34374193, 2021). "Moreover, we found that NEK8 was partially expressed both in astrocytoma and oligodendroglioma." (PMID 34374193, 2021).